BGLAP (bone gamma-carboxyglutamate protein)
Diseases named in the same sentence as BGLAP in open-access papers:
BGLAP is named in the same sentence as 177 diseases in open-access papers, as found by Europe PMC text mining. Sharing a sentence is not in itself a finding about the gene and the disease. The quoted sentences say what the papers report.
osteoporosis (104 papers, 2013 to 2025). A condition of reduced bone mass, with decreased cortical thickness and a decrease in the number and size of the trabeculae of cancellous bone (but normal chemical composition), resulting in increased fracture incidence. "(A) COL1A1 and BGLAP immunohistochemical staining of the femur head from hip dysplasia and osteoporosis patients." (PMID 33006314, 2020). "Our data also revealed an upregulated expression of ALPL and BGLAP in patients with osteoporosis." (PMID 37339951, 2023). "BGLAP and COL1A1 immunohistochemical staining confirmed the decrease in the bone formation marker in osteoporosis patients." (PMID 33006314, 2020). "INS, BGLAP, PTH, IGF1, and TNF were the top 5 most studied genes between osteoporosis and DM." (PMID 35719662, 2022). "The q‐PCR analysis showed that miR‐103‐3p levels in osteoporosis patients (T ≤ −2.5) were higher than in control patients (T > −2.5) and that the levels of ALP, BGLAP, and COL1α1 in osteoporosis patients (T ≤ −2.5) were lower than in control patients (T > −2.5)." (PMID 33440070, 2021). "Ectopic expression of circ‐SLC8A1 promoted ALP, BGLAP, SPP1 and BMP4 expression and silenced circ‐SLC8A1 inhibited ALP, BGLAP, SPP1 and BMP4 expression, and it suggested that circ‐SLC8A1 acted as promotive role in the development of osteoporosis." (PMID 34490735, 2021). "Diseases associated with BGLAP include osteitis fibrosa, renal osteodystrophy, and osteoporosis, whereas phenotypes from GWAS related to HPP comprise heel bone mineral density (rs116251020); HPO data were not available for BGLAP." (PMID 41158885, 2025). "Expression levels of ALPL, BGLAP, and TNF were not significantly different between control and osteoporosis groups, but those of ACP5 and CTSK were significantly increased in patients with osteoporosis compared to those in the controls." (PMID 37339951, 2023).
diabetes (44 papers, 2012 to 2025). "Thus, the aim of this research was to explore the association between BGLAP HindIII polymorphism and type 2 diabetes mellitus (T2DM) development in Ukrainian population." (PMID 31886290, 2019).
periodontitis (20 papers, 2018 to 2025). An acute or chronic inflammatory process that affects the tissues that surround and support the teeth. "hPDLSCs obtained from the periodontal ligament (PDL) of patients with periodontitis were used to collect Linc01133, microRNA-30c (miR-30c), and bone gamma-carboxyglutamate protein (BGLAP) expression data, and their expression changes were traced during osteogenic differentiation of hPDLSCs." (PMID 35435112, 2022).
Obesity (15 papers, 2015 to 2025). Accumulation of substantial excess body fat. "Then, we have prepared regression models with interaction terms in order to explore the association between BGLAP HindIII genotypes and T2DM development depending on sex and the presence of obesity (BMI ≥ 30 kg/m2)." (PMID 31886290, 2019). "Thus, neither obesity nor gender was detected as effect modifier in the association between HindIII SNP of BGLAP promoter region and T2DM development among Ukrainians." (PMID 31886290, 2019).
osteosarcoma (15 papers, 2007 to 2025). A usually aggressive malignant bone-forming mesenchymal neoplasm, predominantly affecting adolescents and young adults. "Since the discovery of BGLAP secretion in a subset of osteosarcoma cell lines, BGLAP has been implicated in the development of various malignant tumors." (PMID 18163903, 2007). "It is well known that abnormal expression of RUNX2, ALPL, and BGLAP determines impaired molecular and cellular functions in Mg-63 and Saos-2, but this phenomenon is different in the two osteosarcoma cell lines." (PMID 31236409, 2019). "Based on the analysis above, we supposed that biochanin A can suppress the proliferation of osteosarcoma and regulate the expression of BGLAP, BAX, and ATF3, which are involved in regulating DSB response, differentiation and cell death of osteosarcoma." (PMID 30723510, 2019). "BGLAP is a small protein (10.9 kDa) that is secreted by osteosarcoma cells and is involved in bone turn-over of metastatic lesions from tumors such as prostate and breast cancers." (PMID 18163903, 2007). "Biochanin A can effectively suppress the proliferation of osteosarcoma and regulate the expression of BGLAP, BAX, and ATF3, which may act as the potential therapeutic targets of osteosarcoma." (PMID 30723510, 2019). "In this study, after the treatment of biochanin A, a decreasing trend of BGLAP level can be seen from the western-blot, which may also indicate the death of osteosarcoma cells." (PMID 30723510, 2019).
prostate carcinoma (13 papers, 1997 to 2025). A carcinoma that arises from epithelial cells of the prostate gland. "In order to characterize ongoing bone cell activity in clinical cases of prostate cancer bone metastasis, we selected a set of genes to represent osteoclast activity (ACP5, CTSK, MMP9), osteoblast activity (ALPL, BGLAP, RUNX2) and osteocytes (SOST)." (PMID 29670000, 2018).
breast carcinoma (11 papers, 2007 to 2024). "A previous study reported that BGLAP was associated with advanced breast cancer staging." (PMID 38259456, 2023). "In breast cancer, BGLAP serum levels determine the progress of the disease, especially with respect to bone metastases." (PMID 18163903, 2007). "Breast cancer cells, once nested to bone, undergo partial osteomimicry by acquisition of typical bone cell markers including ICAM-1, CDH11, OPN, osteonectin (SPARC), osteocalcin (BGLAP) and cellular communication network factor 3 (CCN3)." (PMID 34831167, 2021).
multiple myeloma (4 papers, 2007 to 2023). "In multiple myeloma, BGLAP is considered a biochemical marker for bone resorption and dynamics during the malignant process." (PMID 18163903, 2007). "Thus, serum BGLAP levels are reduced in patients with multiple myeloma with osteolytic bone lesions." (PMID 18163903, 2007).
periodontal disease (4 papers, 2023 to 2025). "Four of them, IL1B (p = 0.023), IL1RN (p = 0.048), BGLAP (p = 0.0372) and PTK2 (p = 0.0075) were down-regulated in the periodontal disease and implant rejection group, and only one was overexpressed: FOXO1A (p = 0.0552)." (PMID 37175429, 2023).
Hypercalcemia (3 papers, 2015 to 2020). An abnormally increased calcium concentration in the blood. "Based on these data, Cmpd3 presented a VDRM selective activation profile of BGLAP over TRPV6 with significantly lower hypercalcemia liability (75.9 vs 17.4% Max." (PMID 29030554, 2017). "The natural agonist 1,25D3 exhibited potent hypercalcemia effects and enhanced activation profiles in both BGLAP (EC50 = 4.10 nM, 100% Max." (PMID 29030554, 2017). "Compounds were tested for their hypercalcemia liabilities in BGLAP and TRPV6 qPCR gene activation assays." (PMID 29030554, 2017).
pancreatic cancer (3 papers, 2007 to 2023). "BGLAP was present in the cytoplasm and occasionally in the nuclei of pancreatic cancer cell lines as determined in the four cultured pancreatic cancer cell lines by immunocytochemistry." (PMID 18163903, 2007). "BGLAP is expressed in pancreatic cancer cells, where it potentially increases pancreatic cancer cell growth and invasion through autocrine and/or paracrine mechanisms." (PMID 18163903, 2007). "In line with this argument, down-regulation of BGLAP levels using siRNA molecules resulted in a significant reduction in pancreatic cancer cell growth and invasion." (PMID 18163903, 2007). "In order to determine the role of BGLAP in regulating the growth and invasion of pancreatic cancer cells, BGLAP was silenced using siRNA molecules in Aspc-1 and Panc-1 pancreatic cancer cells." (PMID 18163903, 2007). "BGLAP is highly expressed in pancreatic cancer cells and promotes tumor growth and invasion." (PMID 37564213, 2023). "Furthermore, BGLAP expression was found in the cancer cells in PDAC tissues as well as in 4 cultured pancreatic cancer cell lines." (PMID 18163903, 2007). "Since BGLAP was expressed in pancreatic cancer tissues and cells, various growth factors that might be involved in pancreatic carcinogenesis were examined for their effect on BGLAP expression." (PMID 18163903, 2007). "Among those factors, only TNF-α reduced the expression of BGLAP in pancreatic cancer cell lines." (PMID 18163903, 2007). "TNFalpha reduced BGLAP mRNA and protein expression levels in pancreatic cancer cell lines." (PMID 18163903, 2007). "In conclusion, BGLAP is expressed in the tubular complexes and cancer cells of CP and PDAC tissues and has the potential to increase pancreatic cancer cell growth and invasion." (PMID 18163903, 2007). "In a subsequent step, the expression of BGLAP was determined in Aspc-1, Capan-1, Panc-1 and T3M4 cultured pancreatic cancer cells." (PMID 18163903, 2007). "The down-regulation of BGLAP by TNF-α in pancreatic cancer cells indicates that BGLAP is one of the TNF-α targets and indirectly suggests a tumor-promoting function of BGLAP in pancreatic cancer." (PMID 18163903, 2007).
prediabetes (3 papers, 2018 to 2022). "The PBMC-isolated from 25 patients with prediabetes (25/28) expressed ALPL, BGLAP, COL1A1, and RUNX2/PPAR and the PBMC-isolated from 15 patients with normoglycemia (15/17) expressed those genes." (PMID 35237235, 2022).
craniosynostosis (1 paper, 2018). Craniosynostosis is defined as the premature fusion of one or more cranial sutures leading to secondary distortion of skull shape resulting in skull deformities with a variable presentation. "Based on our observations, we hypothesize that the CNV results in the general overexpression of BGLAP that may have occurred also locally during osteogenesis in fusing cranial sutures, leading to the craniosynostosis observed in our patient." (PMID 29845577, 2018).
hemophilia (1 paper, 2022). Hemophilia is a genetic disorder characterized by spontaneous hemorrhage or prolonged bleeding due to factor VIII or IX deficiency. "Concentrations of BGLAP and CH3 were compared with MI and PMI values in patients with and without hemophilia." (PMID 35743462, 2022).
lipoma (1 paper, 2018). A benign, usually painless, well-circumscribed lipomatous tumor composed of adipose tissue. "Although there are no studies on gene expression in isolated cells some research groups investigated the differences in expression of ADIPOQ, LEP and PPARG, RUNX2 and BGLAP in lipoma tissue and compared it with normal adipose tissue." (PMID 30544806, 2018).
renal cell carcinoma (1 paper, 2023). "In the GSE54460 renal cell carcinoma dataset, the expression level of COL1A1 was higher in the positive surgical margin group, and the P-value was less than 0.05, but the expression level of BGLAP was not correlated with the positive surgical margin." (PMID 37564213, 2023).
sarcoma (1 paper, 2024). A usually aggressive malignant neoplasm of the soft tissue or bone. "Then, we analyzed the expression of biomarkers of osteoblasts (COL1A1, BGLAP and RUNX2), chondrocytes (COL2A1, COMP and SOX9) and sarcoma (POSTN and DCN), adipocyte (LPL and PPARG) and BMSCs." (PMID 39715773, 2024).
tumor (23 papers, 2007 to 2024). "Therefore, higher BGLAP expression might indicate complete remodeling of the tumor microenvironment and cause a relatively low tumor purity." (PMID 33240930, 2020). "We focused on two regulators, COL1A1 and BGLAP, and observed their significantly positive correlation with most tumor-infiltrating immune cells." (PMID 37564213, 2023). "And more COL1A1 and BGLAP are expressed in the tumor than normal prostate by analyzing the spatial transcriptomics data." (PMID 37564213, 2023). "Consistent with the expectation, the expression of COL1A1 and BGLAP was higher in tumor tissues than in normal tissues, and high expression of COL1A1 and BGLAP was associated with higher GS and BCR rate (P < 0.01)." (PMID 37564213, 2023). "In prostate cancer, BGLAP is expressed in the cancer cells and improves adhesion, proliferation, and survival of tumor cells metastasizing to the bone." (PMID 18163903, 2007). "And more COL1A1 and BGLAP are expressed in the tumor than in the normal prostate." (PMID 37564213, 2023). "Moreover, genes representing mesodermal or/and endodermal tissue differentiation (ACP5, ACTA2, BGLAP, CTSK, DESMIN, FOXA2) were activated in tumor." (PMID 33468253, 2021). "The correlation between osteomimicry and tumor purity was then investigated, and result showed that SPARC and SPP1 expression had a moderate-to-strong and positive correlation with tumor purity, while BGLAP expression had a poor-to-moderate and negative correlation with tumor purity." (PMID 33240930, 2020). "BGLAP was correlated to advanced tumor stage in BRCA, but showed no prognostic value." (PMID 33240930, 2020).
cancer (10 papers, 2007 to 2025). A tumor composed of atypical neoplastic, often pleomorphic cells that invade other tissues. "In addition to COL1A1 and BGLAP, the other six genes in the signature have been reported to be associated with cancers in both basic and clinical studies." (PMID 37564213, 2023). "Moreover, we determined that the two regulators acted as the pan-cancer fitness gene 21, and DepMap data also reminded that COL1A1 and BGLAP were essential genes in almost all cancer types." (PMID 37564213, 2023). "This might indicate that BGLAP is expressed in the disease-specific tissue elements such as the tubular complexes, PanINs and cancer cells." (PMID 18163903, 2007). "Each osteomimetic marker harbored prognostic value in the pan-cancer analyses [SPARC: hazard ratio (HR) = 1.10, p = 0.028; SPP1: HR = 1.25, p < 0.001; BGLAP: HR = 1.13, p = 0.005]." (PMID 33240930, 2020). "BGLAP expression was positively and significantly correlated to TNFRSF25 in all these cancer types except CESC." (PMID 33240930, 2020). "Correlations between the expression level of BGLAP, SPARC, and SPP1 in different cancer types." (PMID 33240930, 2020). "Interestingly, BGLAP was localized in the tubular complexes and PanIN lesions of both CP and PDAC as well as in the cancer cells in PDAC." (PMID 18163903, 2007). "However, no prominent correlation was found between BGLAP expression and immune cell infiltration (R2 < 0.40 for all cancer types and all the six immune cell types)." (PMID 33240930, 2020). "Next, we pooled all the 20 cancer types and found that all the three markers were prognosticator of solid cancers (SPARC: HR = 1.10, 95% CI = [1.01, 1.20], p = 0.028; SPP1: HR = 1.25, 95% CI = [1.14, 1.36], p < 0.001; BGLAP: HR = 1.13, 95% CI = [1.04, 1.24], p = 0.005)." (PMID 33240930, 2020). "Notably, FUT11, BGLAP, SSR2, TGFBR1, BSG, and FUCA1 have been reported to be associated with related cancer, but no studies showed the functions of other eight DESPGs in corresponding cancers." (PMID 31824949, 2019). "However, since cytoplasmic expression of BGLAP was also observed in tubular complexes and cancer cells, it could be speculated that BGLAP is not efficiently released from these cells." (PMID 18163903, 2007). "However, in previous studies, SPARC/SPP1/BGLAP was deemed independent functional molecule rather than marker of osteomimicry, and was investigated separately in different cancer types and no one had combined these molecules and explored their prognostic value in pan-cancer analyses." (PMID 33240930, 2020).
infection (7 papers, 2010 to 2025). The state of being infected such as from the introduction of a foreign agent such as serum, vaccine, antigenic substance or organism. "Relative mRNA expression of BGLAP was significantly reduced in the High group when compared with the Control (P < 0.05), confirming that the severe infection of Eimeria adversely affected long bone growth." (PMID 36635321, 2023).
BGLAP also shares sentences with these, for which no sentence is quoted: Insulin resistance (21 papers); Anxiety (18); type 2 diabetes mellitus (18); Hyperglycemia (15); atherosclerosis (14); Osteopenia (14); Cognitive impairment (13); Glucose intolerance (11); depression (9); metabolic syndrome (9); coronary atherosclerosis (8); Alzheimer disease (7); calcification (6); osteoarthritis (6); chronic kidney disease (5); Hypertension (5); metabolic disorder (5); neurodegenerative disease (5); Parkinson disease (5); Stroke (5); bone disorder (4); bone metastasis (4); cardiovascular disease (4); cognitive decline (4); coronary artery disease (4); postmenopausal osteoporosis (4); Arthritis (3); diabetic kidney disease (3); ischemic stroke (3); lipid metabolism disorders (3).
A further 127 diseases each share a sentence with BGLAP in 3 papers or fewer.